BCL2 (BCL2 apoptosis regulator)
Diseases named in the same sentence as BCL2 in open-access papers (continued):
Sharing a sentence is not in itself a finding about the gene and the disease.
acute leukemia (31 papers, 2012 to 2026). A clonal (malignant) hematopoietic disorder with an acute onset, affecting the bone marrow and the peripheral blood. "Vitexin induces apoptosis via modulation of HIF-1α/Bcl-2/caspase-3 pathway and potentiates efficacy of daunorubicin, thereby supporting potential as an adjunctive therapeutic in acute leukemia." (PMID 41392176, 2025). "BCL-2 functions in cooperation with PML-RARA fusion protein to promote acute leukemia and prevent neutrophil differentiation." (PMID 40386562, 2025). "In preliminary clinical trials in acute leukemias, when combined with chemotherapy, it demonstrated biological activity by significantly reducing BCL2 mRNA expression levels." (PMID 38338698, 2024). "The first pharmacological approach tested in patients with acute leukemias was the anti-sense oligonucleotide Oblimersen sodium (Genasense), which targets the first six codons (the initiation codon region) of BCL2 mRNA." (PMID 38338698, 2024). "Studies aim to determine the activity of BCL-2 inhibitor in the treatment of both primary and refractory acute leukemias in combination with standard and high-dose chemotherapy." (PMID 38069030, 2023). "This, and the fact that various agents were identified that already have been shown to be effective against KMT2A-rearranged acute leukemia, such as BCL-2 inhibitors, HDAC inhibitors, and SN-38, clearly demonstrated the validity of our drug screens." (PMID 35327440, 2022). "At the 10 nm drug concentration, we identified Venetoclax, a well-studied BCL2 inhibitor known to be highly active against KMT2A-rearranged acute leukemia." (PMID 35327440, 2022). "For instance, quercetin caused apoptosis in different cancerous cell lines, and inhibited the formation of Bcl-2 proteins in different tumor cells such as the acute leukemia cell line HL-60." (PMID 33808594, 2021). "In another phase 1 combination trial of oblimersen in acute leukemia patients levels of Bcl-2 transcripts were measured in bone marrow cells of 12 patients after 5 days of treatment, prior to chemotherapy." (PMID 22989709, 2012). "Therefore, we conclude that METTL3 likely plays a role in sustaining the expression of c-Myc and BCL2 in specific acute leukemia cells, particularly implicating its involvement in c-Myc regulation." (PMID 40453361, 2024). "However, upregulation of Bcl-2 is common in acute leukemia and a decreased Bax/Bcl-2 ratio correlates with poor response to therapy." (PMID 34617137, 2021). "This approach is demonstrated in the recent promising results achieved utilizing venetoclax, a BCL2 inhibitor, in patients with PICALM::MLLT10 acute leukemia." (PMID 41532548, 2026). "Other BH3-mimetics, such as ABT-199 (venetoclax, BCL-2 inhibitor), FDA approved for chronic and acute leukemia, or ABT-263 (navitoclax, BCL-2 and BCL-xL inhibitor), are in clinical trials despite their associated hematological side effects." (PMID 32024199, 2020). "In high BCL-2-expressing acute leukemia cells with resistance to TRAIL, XIAP inhibitors were able to induce cleavage of BCL-2 proteins and promote MOMP through conformational change of BAK, further enhancing TRAIL-induced apoptosis." (PMID 31652776, 2019). "For instance, classical dendritic cells (CDC), stem cellleukemia (SCL) and B Cell Lymphoma-2 (BCL-2) are themain targets for down-regulated miRNA." (PMID 29633597, 2018). "Despite these uncertainties, BCL-2 inhibition with venetoclax, and MCL-1 or BCL-XL inhibition potentially, represent a significant advance in targeted treatment approaches to hematologic malignancies and are very promising in acute leukemia and MDS treatment." (PMID 30972300, 2019).
asthma (31 papers, 2008 to 2026). "Interestingly, in alveolar lavage fluid, BCL2 was elevated in asthmatics with increasing asthma severity, which may be related to inhibition of apoptosis by BCL2, increasing the risk of severe asthma cancer." (PMID 40160461, 2025). "B-cell lymphoma 2 (BCL2) is primarily an anti-apoptotic protein, and apoptotic biological processes are involved in asthma and COPD." (PMID 40160461, 2025). "The results of our analysis revealed that DEHP, DOP affected asthma through BCL2, whereas DEHP and DEP and DOP affected COPD through BCL2." (PMID 40160461, 2025). "B-cell lymphoma 2 (BCL2) is mainly an anti-apoptotic protein and is involved in the biological process of apoptosis in asthma and COPD." (PMID 40160461, 2025). "Further western blot analysis has shown that CAD decreased cell apoptosis-associated Bax and Cleaved caspase-3 protein levels, while as increased Bcl-2 protein levels in lung tissues of asthma mice." (PMID 36213326, 2022). "And miR-23a is reportedly involved in the pathogenesis of asthma by targeting BCL2 in airway epithelial cells and CXCL12 in fibroblasts." (PMID 35927714, 2022). "As we have known, the Bcl-2/Bax/Cleaved caspase-3 signaling pathway has been reported in regulating cell apoptosis and survival in many diseases, including asthma." (PMID 36213326, 2022). "The protein ratio of Bcl-2/Bax was notably increased in the asthma group vs. the control group (P < 0.05)." (PMID 32831860, 2020). "Bcl-2 protein and mRNA were significantly upregulated, while Bax protein and mRNA were downregulated in asthma group vs. control group (all P < 0.01)." (PMID 32831860, 2020). "Compared with the asthma or Bud group, Bcl-2/Bax was significantly decreased in EEL and Bud&EEL groups (P < 0.05 or 0.01)." (PMID 32831860, 2020). "Second, asthmatics demonstrated increased numbers of cells positive for the anti-apoptotic molecule Bcl-2 compared to normal control subjects, and the expression of Bcl-2 correlated with severity of asthma." (PMID 30425708, 2018). "Acupuncture at ST36 also regulates the disorders of Fas and Bcl-2 mRNA expression, promotes the apoptosis of eosinophils, and consequently inhibits the development of inflammatory reaction of asthma in rats." (PMID 28810910, 2017). "The expression of Bax, Caspase-3 and Bcl-2 of lung tissue of asthma mice was analyzed using Western blotting." (PMID 27801673, 2016). "Consistent with the RT-qPCR results, protein level of the anti-apoptosis gene Bcl-2 was significantly impaired in the testis of asthma mice, while the expression of AIF and HIF-1α was significantly induced in the asthmatic testis." (PMID 26938720, 2016). "Following an asthma exacerbation, an increase in Bcl-2 expression in BAL lymphocytes has been shown, but contrary to our study, these asthmatics had a FEV1 that ranged between 62 and 83 % predicted, compared with 98 % in our current study." (PMID 26303256, 2015). "It was found that the survival of PBL in asthmatic patients was higher than in HV and increases with asthma severity, represented by increasing Bcl-2/Bax ratio." (PMID 19087256, 2008). "In an ovalbumin-lipopolysaccharide (OVA-LPS)-induced animal model of asthma, bronchioalveolar epithelial cells in the lungs were found to undergo apoptosis through the activation of p38 MAPK, inhibition of Bcl-2, and induction of B-cell lymphoma 2 (Bcl-2)-associated X protein (Bax)." (PMID 39421735, 2024).
asthma (continued). "Consistent with previously published research, in this study, we have found that CAD or CAD-contained serum observably weakened the levels of Bax and Cleaved caspase-3 protein and increased Bcl-2 expressions in asthma mice and LPS-induced 16HBE cells, respectively." (PMID 36213326, 2022). "Furthermore, the number of cells expressing the Bcl-2 antiapoptotic molecule was increased in asthmatic patients and correlated with asthma severity." (PMID 31637021, 2019). "Similarly, asthmatic patients demonstrated an increased number of cells expressing the anti-apoptotic molecule Bcl-2 compared to normal control subjects, and the expression of Bcl-2 correlated with severity of asthma." (PMID 30443253, 2018). "Together with the observation of Bcl-2/Bax involvement, these results collectively suggest that asthma may lead to the activation of mitochondrial pathway of apoptosis." (PMID 26938720, 2016). "Consistent with the PCR array data, the transcriptional expression of Bcl-2, an anti-apoptosis factor, was markedly decreased in the testis of asthma mice, while the mRNA transcription of pro-apoptosis genes including Bax, BNIP3, caspase-9 and AIF were enhanced significantly in asthmatic testis." (PMID 26938720, 2016). "In this study, we report that AECs exhibit a proapoptotic phenotype when exposed to asthma-related proinflammatory cytokines, and cIAP2 in partnership with cIAP1 and Bcl2, may be primary factors blocking commitment to apoptosis." (PMID 24303189, 2013). "Moreover, memory cells, CD45RO+ and CD45RO+/CD45RA+ ratio were correlated directly with Bcl-2/Bax, in severe and mild asthma patients." (PMID 19087256, 2008). "The increase in Bcl-2 could therefore be related to asthma severity." (PMID 26303256, 2015). "PTGS2, IL10, CTSB, JAK2, and MTOR were significantly downregulated in alveolar lavage fluid with increasing asthma severity, while MMP9, GSK3B, BCL2, EGFR, and CCND1 were upregulated." (PMID 40160461, 2025). "PPI network analysis showed that PTGS2, BCL2, and CASP3 were the key predictive targets of QJWJ in treating asthma." (PMID 39889171, 2025). "In an OVA-LPS-induced animal asthma model, anti-apoptotic effects were observed in the lung system through increased activation of p38 MAPK (p-p38 MAPK), inhibition of Bcl-2, and induction of Bax." (PMID 39421735, 2024). "In a rat model of asthma, nebulized TP can inhibit ASM hyperplasia by down-regulating NF-κB, bcl-2, and PI3K, but details of how to instil aerosolized TP into the airway were limited." (PMID 37645252, 2023). "DNA ladder and immunochemistry showed significant increase in apoptotic index of the asthmatic testis, whereas a decrease in mRNA expression of Bcl-2 and increases in Bax, BNIP3, caspase-9, and AIF were observed in the asthma group." (PMID 26938720, 2016). "Compared with asthma group, the positive area of Bcl-2 was remarkably decreased, whereas the positive area and IOD of Bax were increased in all three treatment groups (P < 0.05 or 0.01); EEL and Bud&EEL reduced significantly the IOD of Bcl-2 (all P < 0.01)." (PMID 32831860, 2020). "Similarly, in the lung tissues of asthma mice, the protein levels of Bax and Cleaved-Caspase-3 were significantly lower in the PMA group than those of control group; and Bcl-2 protein level was significantly higher than control group." (PMID 27801673, 2016). "However, B-cell lymphoma 2 (BCL2) expression was lower, and SCGB1A1 was higher in asthmatics compared to control, which contrasts with results in severe asthma in horses and may be due to different experimental design and different phases of disease being assessed." (PMID 28886691, 2017).
head and neck squamous cell carcinoma (31 papers, 2011 to 2026). A squamous cell carcinoma that arises from any of the following anatomic sites: lip and oral cavity, nasal cavity, paranasal sinuses, pharynx, larynx, and salivary glands. "Cell death in head and neck squamous cell carcinoma (HNSCC) is mediated by the perforin/granzyme pathway associated with the activity of the membrane pro-apoptotic protein Bcl-2." (PMID 35874714, 2022). "We have previously shown that tumors from patients with head and neck squamous cell carcinoma exhibit significantly higher expression of Bcl-2 in tumor-associated endothelial cells." (PMID 26509633, 2015). "Anti-apoptotic roles for HOXC6 have also been described in head and neck squamous cell carcinoma in which HOXC6 directly increases the promoter activity causing overexpression of Bcl-2." (PMID 24708576, 2014). "Bcl-2-positivity also results in a better response to radiotherapy in head and neck squamous cell carcinoma." (PMID 37370810, 2023). "In one RCT, Bcl-2 was targeted by the Bcl-2 inhibitor AT-101 to boost radiotherapy efficiency in head and neck squamous cell carcinoma (HNSCC)." (PMID 36185861, 2022). "B-cell lymphoma 2 (Bcl-2) Inhibitor AT-101 leads to potentiation of radiotherapy-dependent apoptosis in head and neck squamous cell carcinoma in vitro, which further encourages the use of AT-101 in Bcl-2 expressing malignancies." (PMID 36185861, 2022). "Evaluate combined effects of radiation and B-cell lymphoma 2 (Bcl-2) inhibitor AT-101 in head and neck squamous cell carcinoma (HNSCC)." (PMID 36185861, 2022). "TTP enhances cisplatin sensitivity of squamous cell carcinoma of the head and neck (SCCHN) by inhibiting Bcl-2 expression at the post-transcriptional level, thereby enhancing cell apoptosis." (PMID 34026612, 2021). "In particular, high endogenous expression of the anti-apoptotic BCL2 family members BCL2 and BCL-xL was associated with increased cisplatin resistance in a large panel of head and neck squamous cell carcinoma cell lines." (PMID 29462944, 2018). "HOXC6 is also deregulated in human head and neck squamous cell carcinoma and modulates Bcl-2 expression." (PMID 27081081, 2016). "In head and neck squamous cell carcinoma, MiCU1 expression is elevated, and inhibiting MiCU1 disrupts mitochondrial calcium homeostasis and membrane potential stability, thereby inhibiting apoptosis and reducing Bcl-2 expression." (PMID 38911376, 2024). "In addition to producing proinflammatory factors, the PI3K/Akt pathway has been shown to suppress apoptosis via inactivation of caspase 3/7 and activation of B-cell lymphoma 2 (Bcl-2) protein in head and neck squamous cell carcinomas." (PMID 38895635, 2024). "NFs inhibit head and neck squamous cell carcinoma (HNSCC) tumor growth and target B-cell lymphoma-2 (BCL2) expression in vivo through the transfer of exosomes containing miR-3188, which are significantly reduced with the transition to CAFs." (PMID 37046676, 2023). "Our data demonstrate that depletion of the RNA-binding protein La in head and neck squamous cell carcinoma cells (HNSCC) increases the sensitivity toward cisplatin-induced cell death paralleled by reduced expression of the anti-apoptotic factor Bcl2." (PMID 27105491, 2016). "Bak protein was upregulated, whereas Bcl-2 was downregulated in the KDM5B-knockdown cells, indicating KDM5B maintained head and neck squamous cell carcinoma survival by regulating Bcl family members." (PMID 35333349, 2022). "Overexpression of antiapoptotic proteins such as BCL2, BCL2L1/BCL-XL, and MCL1, on the other hand, negatively correlates with response to cisplatin in ovarian or head and neck squamous cell carcinoma (HNSCC) patients." (PMID 34645978, 2021). "In head and neck squamous cell carcinoma, HOXC6 inhibits apoptosis via Bcl-2 regulation." (PMID 27081081, 2016).
head and neck squamous cell carcinoma (continued). "•Cisplatin resistance is common in head and neck squamous cell carcinoma (HNSCC) and may be mediated by anti-apoptotic pathways, including Bcl-2, which is not specifically targeted in routine patient care." (PMID 39970625, 2025).
lupus (30 papers, 2006 to 2025). "Bcl-2 is a bridge between oxidative stress and apoptosis, and some polymorphisms are associated with lupus." (PMID 39061948, 2024). "Both studies showed evidence of a lupus-like illness caused by continuous expression of Bcl-2, thereby inhibiting apoptosis of autoreactive B lymphocytes." (PMID 37993903, 2023). "We show here that the expansion of TFH cells in lupus-prone TC mice is associated with an increased expression of Bcl2." (PMID 30348969, 2018). "In B lymphocytes the overexpression of bcl-2 has been associated with anti-nuclear activity, such as occurs in lupus." (PMID 24834112, 2014). "In our study, chronic neuroinflammation in lupus mice triggered by chronic activation of the TLR7 pathway seemed to induce an increase in Bcl-2 expression in the brain tissue as a compensatory neuroprotective mechanism against chronic oxidative stress." (PMID 39061948, 2024). "Although a significant increase in BCL-2 level is reported in T cells in patients with systemic lupus erythematosus, there are few studies on BCL-2 in T cells of patients with CLL." (PMID 35193595, 2022). "At the same time, the expression levels of pro-apoptotic proteins Bim and Bax in MDSCs of Dectin3−/− mice with lupus significantly increased, and the expression of anti-apoptotic protein Bcl2 significantly decreased." (PMID 34480018, 2021). "And the protein expressions of Bim and Bax increased in MDSCs from Dectin3−/− lupus mice compared with WT lupus mice; however, the expression of Bcl2 in MDSCs of Dectin3−/− mice with lupus was lower than that in WT mice with lupus." (PMID 34480018, 2021). "In sum, lupus TC mice show an expansion of TFH cells that precedes the production of autoantibodies, and that is associated with increased mTORC1 activity and Bcl2 expression, as well as decreased STAT3 activation." (PMID 30348969, 2018). "Bcl-2 is an anti-apoptotic factor that plays a role in persistence of pathogenic pDCs, which are the source of Type I IFN in lupus." (PMID 32185249, 2017). "Studies in pDCs derived from NZB/W F1 mica as well as from humans (healthy controls and patients with lupus) reveal that exposure to Bcl-2 antagonists ABT-737 and ABT-199 reduces survival of these pDCs." (PMID 32185249, 2017). "Newer therapeutic strategies being investigated in preclinical models of lupus that reduce the production of Type I interferons include dihydroartemisinin, Bruton’s tyrosine kinase antagonists, Bcl-2 antagonists and sphingosine-1 phosphate agonists." (PMID 32185249, 2017). "On the other hand, pDCs appear to be able to survive better in lupus, as their expression of antiapoptotic Bcl-2 was found to be increased." (PMID 27034965, 2016). "Consistently, IL-17 has been implicated in modulating the expression levels of prosurvival Bcl-2 family proteins, including Bcl-2 (B-cell lymphoma 2) and Bfl-1/A1 (Bcl-2 family member) in some autoimmune diseases such as systemic lupus erythematosus." (PMID 26504859, 2015). "A similar pattern of BCL-2 was found in the NZB/WF1 mouse model of lupus." (PMID 39080788, 2024). "Interestingly, increased levels of miR-29b and miR-29c, targeting anti-apoptotic member Bcl-2 have been observed in lupus pDCs after the administration of glucocorticoids, as well as in lupus T cells." (PMID 28035990, 2016). "BCL-2 overexpression in these animals leads to autoimmunity similar to that measured in patients with systemic lupus erythematosus (SLE)." (PMID 28066751, 2016). "Preclinical studies show that BH3 mimetics such as ABT-737, which targets BCL2, BCLXL, and BCLW, can suppress T and B cell proliferation in lupus and arthritis models." (PMID 41155156, 2025). "Several Bcl-2 inhibitors have already entered clinical trials for various cancers and recently, a phase I study with ABT-199 in systemic lupus erythematosus patients has been completed." (PMID 26973650, 2016).